CEACAM7 (CEA cell adhesion molecule 7)
Synonyms: CGM2; CEA
Tractability: Antibody: UniProt places it where antibodies can reach, with high confidence; its Gene Ontology location is reachable by antibodies, with high confidence; UniProt predicts a signal peptide or a membrane-spanning region; the Human Protein Atlas places it where antibodies can reach.
Gene: Protein-coding gene on chromosome 19 (41,673,298 to 41,706,976, reverse strand). Ensembl gene ENSG00000007306.
Subcellular location: Cell membrane; Apical cell membrane
Subcellular location (Human Protein Atlas): Plasma membrane; Cytosol
Pathways (Reactome):
Metabolism of proteins: Post-translational modification: synthesis of GPI-anchored proteins
Gene Ontology:
Molecular function: protein tyrosine kinase binding
Biological process: regulation of immune system process; signal transduction
Cellular component: apical plasma membrane; plasma membrane; cell surface; extracellular region
Genetic constraint (gnomAD): Loss-of-function variants: 23 observed, 23.73 expected, observed/expected ratio (o/e) 0.97, 90% interval 0.7 to 1.37. The upper end of that interval is the gene's LOEUF score, 1.37, which puts it in group 5 of 6, group 1 being the genes least tolerant of losing a copy. Missense variants: 308 observed, 320.97 expected, observed/expected ratio (o/e) 0.96, 90% interval 0.87 to 1.05. Synonymous variants: 133 observed, 123.74 expected, observed/expected ratio (o/e) 1.07, 90% interval 0.93 to 1.24.
Homologues: Orthologues: chimpanzee CEACAM7 (98% identical), macaque CEACAM7 (86% identical). Paralogues in human: CEACAM5 (68% identical), CEACAM8 (68% identical), CEACAM1 (66% identical), CEACAM6 (65% identical), PSG8 (51% identical), PSG1 (50% identical), PSG6 (50% identical), PSG2 (49% identical), PSG11 (49% identical), PSG9 (49% identical), PSG7 (48% identical), PSG4 (48% identical), and 12 more.
Diseases named in the same sentence as CEACAM7 in open-access papers:
CEACAM7 is named in the same sentence as 33 diseases in open-access papers, as found by Europe PMC text mining. Sharing a sentence is not in itself a finding about the gene and the disease. The quoted sentences say what the papers report.
colon carcinoma (6 papers, 2011 to 2025). "As CEACAM7 levels in cancer patients correlate with the duration of their cancer diagnosis, future studies should investigate CEACAM7 alterations in long-term sufferers of UC, who are at a higher risk to develop colon cancer, as a potential diagnostic biomarker." (PMID 34394073, 2021). "To ensure this positive co-expression pattern between PDE9A and CEACAM7, we also look into TCGA colon cancer patient data via UCSC Xena." (PMID 34016083, 2021). "This positive interaction was confirmed by adopting the Oncomine database which ensured that CEACAM7 was also under-expressed in colon cancer tissues." (PMID 34016083, 2021). "Similarly, a broad reduction in cell adhesion markers including CEACAM1, CEACAM5, CEACAM6, and CEACAM7 occurs in human colon cancer cell lines after treatment with chloroquine." (PMID 39900438, 2025). "R2 database and TCGA colon cancer patients data from UCSC Xena also ensured the positive correlation between PDE9A and CEACAM7." (PMID 34016083, 2021). "DUOXA2, CEACAM7, and the proto-oncogene ADRA1B were downregulated by calcitriol in rectal tumor organoids, but upregulated in colon tumor organoids." (PMID 32824266, 2020). "In colon cancer, CEA is upregulated, but CEACAM7 was reported to be downregulated, it is interesting that they were both upregulated in gastric cancer, and co-expressed in most of the tissues." (PMID 22195770, 2011).
colorectal cancer (6 papers, 2007 to 2024). A primary or metastatic malignant neoplasm that affects the colon or rectum. "The expression of CEACAM7 encoding a cell adhesion protein is downregulated in colorectal carcinoma." (PMID 39363341, 2024). "Carcinoembryonic antigen-related cell adhesion molecule 7 (CEACAM7) is expressed in normal colon, but reported downregulated in adenomas and colorectal carcinomas." (PMID 17201907, 2007). "Neither CEACAM7 nor CEACAM3 has previously been studied in IBD, although a reduction in CEACAM7 and CEACAM3 was reported in patients in stage II recurrent and non-recurrent colorectal cancer and in the post-operative phase of patients with colorectal cancer, respectively." (PMID 34394073, 2021).
adenoma (4 papers, 2007 to 2021). A neoplasm arising from the epithelium. "The downregulation of CEACAM7 expression in hyperplastic polyps and early adenomas represents some of the earliest observable molecular events leading to CRC." (PMID 32566650, 2020). "However, down-regulation of CEACAM7 in hyperplastic polyps and early adenomas represent some of the earliest observable molecular events leading to colorectal tumors." (PMID 34447411, 2021). "Deregulation of CEACAM-7 expression has been shown to occur early in colorectal oncogenesis; decreased CEACAM-7 expression was shown in adenomas, hyperplastic polyps, and aberrant crypt foci." (PMID 22195770, 2011).
hyperplastic polyp (4 papers, 2007 to 2021). A polyp found mainly in the stomach and colon. "For example, CEACAM7 is a member of the carcinoembryonic antigen family of genes and expression has been documented in highly differentiated normal colon epithelium and the apical surface of normal ductal pancreas epithelium, while loss of expression has been reported in colon hyperplastic polyps." (PMID 17543121, 2007).
breast carcinoma (3 papers, 2018 to 2024). "One variant, CEACAM7 c.195C > A;p.(Y65X), was associated with breast cancer risk in both ethnicities." (PMID 34447411, 2021). "Overall, gene-based aggregation analyses revealed that rare PTVs in CEACAM6, CEACAM7, and CEACAM8 are associated with European American breast cancer risk, and rare PTVs in CEACAM7 are associated with breast cancer risk in African Americans." (PMID 34447411, 2021). "Gene-based aggregation analyses revealed that rare PTVs in CEACAM6, CEACAM7, and CEACAM8 are associated with European American breast cancer risk, and rare PTVs in CEACAM7 are associated with breast cancer risk in African Americans." (PMID 34447411, 2021). "Gene-based analyses determined that rare PTVs in CEACAM6, CEACAM7, and CEACAM8 are associated with European American breast cancer risk, and rare PTVs in CEACAM7 are associated with breast cancer risk in African Americans." (PMID 34447411, 2021). "CEACAM7, which was associated with breast cancer risk in both ethnicities, has no current link to breast cancer." (PMID 34447411, 2021). "How CEACAM7 plays a role in breast cancer is currently unknown, but the link could even be indirect and due to expression in non-breast tissue." (PMID 34447411, 2021). "For instance, PHTF1, MUC5AC, ZNF192, PCSK6, and HDGFRP3 are shown to be involved in breast cancer, and some common genes such as DCT, ZP2, and CEACAM7 might be involved in breast cancer." (PMID 29589558, 2018).
rectal cancer (3 papers, 2010 to 2021). A primary or metastatic malignant neoplasm that affects the rectum. "Some functional proteins were co-expressed with PDE9A like CEACAM7, a prognostication marker for rectal cancer reappearance." (PMID 34016083, 2021). "PDE9A demonstrated the highest positive correlation for rectal cancer recurrence with a marker gene CEACAM7." (PMID 34016083, 2021). "UniProtKB reports CEACAM7 to be strongly downregulated in colonic adenocarcinomas, and it has been reported to be a predictive marker for rectal cancer recurrence." (PMID 29531238, 2018). "CEA-related cell adhesion molecule 7 (CEACAM-7) is down-regulated in rectal cancers relative to normal mucosa and independently predicts recurrence-free survival for stage II rectal cancers." (PMID 21339979, 2010).
asthma (2 papers, 2020 to 2025). "Another asthma-related protein that was increased in T17-derived EVs was CEACAM7, which together with CEACAM6 has been implicated in severe neutrophilic asthma." (PMID 32560723, 2020).
colon adenocarcinoma (2 papers, 2018 to 2020). "In colon adenocarcinoma and rectum adenocarcinoma, the expressions of CEACAM7 and CNTN3 were significantly positively correlated with infiltrating levels of B cells." (PMID 32566650, 2020).
metastatic disease (2 papers, 2007). "Controversially, we found CEACAM7 upregulated in the liver metastases, suggesting another function in the metastatic tumors." (PMID 17201907, 2007). "The data suggest that abundant expression of CEACAM7 and S100A7 collectively, are unique to cervical tissue and have the potential to serve as useful biomarkers in identifying origins of metastatic disease." (PMID 17543121, 2007).
pancreatic cancer (2 papers, 2024 to 2025). "Antigenic targets evaluated for CAR-T for pancreatic cancer in preclinical or clinical models notably include prostate stem cell antigen, mesothelin (MSLN), CEACAM7, CEA, HER2, Mucin-1, FAP, and others." (PMID 40723238, 2025). "Several antigens, such as PSCA, MUC1, claudin, CEA, and carcinoembryonic antigen-related cell adhesion molecule (CEACAM7), have been discovered as potential targets for CAR-T cell treatment in pancreatic cancer." (PMID 38892913, 2024).
chronic atrophic gastritis (1 paper, 2011). Atrophic gastritis that is persistent and long-standing. "Positivity for CEACAM7 expression was found in chronic atrophic gastritis (12%; 6/50), low-grade GIN (29.1%; 16/55), and high-grade GIN (28.9%; 13/45)." (PMID 22195770, 2011). "We found that, compared with gastric normal mucosa, CEACAM7 expression was significantly increased in chronic atrophic gastritis and all other lesions, and CEA expression was significantly increased in GINs and gastric carcinoma." (PMID 22195770, 2011). "We compared the expression patterns of CEACAM7 and CEA systematically in normal mucosa, chronic atrophic gastritis, gastric intraepithelial neoplasia (GIN), and carcinomas of the stomach with consecutive tissue microarray (TMA) sections." (PMID 22195770, 2011). "CEACAM7 expression was localized to the luminal surface of chronic atrophic gastritis and GINs, no immunoreaction was detected in normal mucosa." (PMID 22195770, 2011).
colitis (1 paper, 2025). Inflammation of the colon. "In addition, AIEC LF82 induced colitis in CEABAC10 transgenic mice harboring human CEACAM3, CEACAM5, CEACAM6, and CEACAM7 genes, and intraperitoneal injection of anti-CEACAM6 significantly decreased LF82 colonization." (PMID 41163391, 2025).
dry eye (1 paper, 2019). "Of these proteins, CEACAM7 and RARRES1 have not yet been connected to ocular surface condition and while ACTG1 is an interesting protein, it has so far been only connected to treatment effects of dry eye." (PMID 30976209, 2019).
gastric carcinoma (1 paper, 2011). A carcinoma that arises from epithelial cells of the stomach. "CEACAM7 was more frequently expressed in poorly differentiated tumors than in well and moderately differentiated gastric carcinomas (41.3% vs. 20.0%, P = 0.006)." (PMID 22195770, 2011). "Immunohistochemistry was performed on consecutive sections of 145 gastric carcinomas using either anti-CEACAM7 or anti-CEA antibody." (PMID 22195770, 2011). "CEACAM7 positivity was significantly higher in diffuse-type gastric carcinomas than in intestinal-type gastric carcinomas, (39.7% vs. 22.2%, P = 0.023)." (PMID 22195770, 2011). "CEACAM7 expression was found to be significantly correlated with the differentiation of gastric carcinoma." (PMID 22195770, 2011). "However, the significance of CEA and CEACAM7 expression in precancerous lesions of gastric carcinoma is poorly understood." (PMID 22195770, 2011). "Thus, we hypothesized that CEACAM7 might promote aggressiveness and progression of gastric carcinoma via regulating tumor cell differentiation, and this needs further investigation." (PMID 22195770, 2011). "CEACAM7 and CEA expression was detected by immunohistochemistry in consecutive sections of 345 subjects with gastric carcinoma and precancerous lesions." (PMID 22195770, 2011). "CEACAM7 expression correlates with tumor differentiation and CEA expression in gastric carcinoma." (PMID 22195770, 2011).
pancreatic ductal adenocarcinoma (1 paper, 2022). An infiltrating adenocarcinoma that arises from the epithelial cells of the pancreas. "CAR T-cell therapy targeting CEACAM7 has been reported as a potential treatment for pancreatic ductal adenocarcinomas." (PMID 36081904, 2022).
pharynx cancer (1 paper, 2018). A primary or metastatic malignant neoplasm that affects the pharynx. "Among the five somatic-only variations leading to LOG on CEACAM7 three are observed in skin cancer, the other two in prostate and pharynx cancers, independently." (PMID 29531238, 2018).
prostate carcinoma (1 paper, 2021). A carcinoma that arises from epithelial cells of the prostate gland. "Our results showed low expression of CEACAM7 in the BCR group, suggesting a putative role in the initiation and progression of prostate cancer." (PMID 34133324, 2021).
tumor (12 papers, 2006 to 2025). "We found that four out of the 21 shared ASE genes (HLA-A, HLA-B, HLA-C, and CEACAM7) and showed significant differences in the allele ratios between tumor and normal tissues (paired t-test)." (PMID 30538721, 2018). "Based on the previous study, the primary members CEACAM1 and CEACAM7 were recognized as tumor suppressors, while CEACAM5 and CEAMCAM6 were upregulated in almost 50% types of tumors and functioned as oncogenes." (PMID 36759883, 2023). "Multivariate analysis demonstrated that double-positivity for CEACAM7 and CEA expression (P = 0.004) and tumor stage (P = 0.001) were factors independently associated with poorer patient prognosis." (PMID 22195770, 2011). "Furthermore, they have shown that CAR-T therapy targeting CEACAM7 can result in remission of late-stage patient derived PDAC xenograft tumours in immunodeficient murine models for aggressive metastatic disease." (PMID 37686543, 2023). "In the analysis around node 2, we observed enrichment of numerous immune-related genes at the starting point, such as IL32 and CEACAM7, indicating that immune regulation might play an important role in early cell state transitions and potentially participate in tumour microenvironment remodelling." (PMID 40539065, 2025). "We found that CEACAM1-S/L, CEACAM7-1/2, MUC2 and CK20 mRNAs were expressed at lower levels in the primary tumour compared to normal colon." (PMID 16755296, 2006). "Other than REG family and dual oxidase genes, microarray analysis suggested that expression of CEACAM6 and CEACAM7, members of the carcinoembryonic antigen-related cell adhesion molecule family, and MUC1, which inhibits the anti-tumor immune response, was upregulated by more than twofold." (PMID 33483567, 2021).
cancer (7 papers, 2011 to 2025). A tumor composed of atypical neoplastic, often pleomorphic cells that invade other tissues. "CEACAM7 plays important role in cancer pathology and may provide valuable information to predict promising prognostic markers of CRC and to unravel the molecular mechanism of CRC." (PMID 34016083, 2021). "suggesting that CEACAM7 may play different roles in different cancers." (PMID 22195770, 2011). "CD74 was previously shown to be decreased in cancer samples based on mRNA levels (NAP/NC ratio log2 − 0.169, CC NM/NC − 1.966 and CC M/NC − 2.601) and CEACAM-7 (NAP/NC ratio log2 − 2.054, CC NM/NC − 3.259 and CC M/NC − 3.911) based on immunohistochemistry staining." (PMID 31889941, 2019).
adenocarcinoma (1 paper, 2022). A common cancer characterized by the presence of malignant glandular cells. "CGM2, now named CEACAM7, was described to be present in leukocytes and adenocarcinoma." (PMID 36361758, 2022).
CEACAM7 also shares sentences with these, for which no sentence is quoted: infection (2 papers); bladder cancer (1); colon (1); colorectal (1); colorectal adenoma (1); colorectal tumors (1); COVID-19 (1); lung adenocarcinoma (1); lymph node metastasis (1); rectal tumor (1); rectum adenocarcinoma (1); skin cancer (1); ulcerative colitis (1).